GCG (glucagon)
Diseases named in the same sentence as GCG in open-access papers (continued):
Sharing a sentence is not in itself a finding about the gene and the disease.
type 2 diabetes (continued). "Type 2 diabetes is associated with elevated glucagon concentration throughout the day, and both type 2 diabetes and impaired glucose tolerance are associated with impaired suppression of glucagon secretion." (PMID 29242971, 2019). "Glucagon secretion by pancreatic α-cells is triggered by hypoglycemia and suppressed by high glucose levels; impaired suppression of glucagon secretion is a hallmark of both type 1 and type 2 diabetes." (PMID 29416045, 2018). "The second major CRR defect is loss of physiological glucagon secretion, which is profound in type 1 diabetes but also present in longer-duration type 2 diabetes." (PMID 29417183, 2018). "We have reported that glucagon-stimulated CPR, following intravenous glucagon administration, was negatively associated with skeletal muscle mass in patients with type 2 diabetes younger than 65 years." (PMID 27612202, 2016). "Type 2 diabetes (T2D) is a chronic metabolic disease resulting from defects in insulin secretion and insulin action and glucagon suppression, which cause hyperglycaemia." (PMID 25710465, 2015). "On the other hand, glucagon also plays a pathogenic role in diet-induced type 2 diabetes, as it is essential in different rodent models of hyperglycemia, and it is an enabler of the diet-induced hyperinsulinemia." (PMID 26909312, 2015). "High blood glucose levels, caused by an imbalance in plasma levels of insulin and glucagon, are characteristic of type 2 diabetes." (PMID 26198634, 2015). "In patients with type 2 diabetes, glucagon secretion is dysregulated, but the underlying mechanisms remain unclear." (PMID 41308986, 2025). "Furthermore, GLP-1 receptor (GLP-1R) agonists are widely used for treating Type 2 diabetes due to their ability to enhance glucose-dependent insulin secretion, reduce glucagon levels, and minimize the risk of hypoglycemia." (PMID 39582948, 2024). "The specific susceptibility to type 2 diabetes in TS might be associated with impaired incretin effect, abnormal glucagon and growth hormone secretion, and intrinsic beta cell abnormalities." (PMID 39274315, 2024). "In obesity and type 2 diabetes, hyperglucagonaemia may be caused by elevated levels of glucagonotropic amino acids due to hepatic glucagon resistance at the level of amino acid turnover." (PMID 38276866, 2024). "The glucagon-to-insulin ratio is strongly linked to hyperglycemia in patients with type 2 diabetes." (PMID 37960324, 2023). "Increased glucagon levels have been linked to the pathogenesis of hyperglycemia in type 2 diabetes." (PMID 37140984, 2023). "Therapeutics directed at olfactory receptor signaling in the pancreas could therefore help reduce excessive glucagon activity associated with diseases such as type 2 diabetes." (PMID 36104518, 2022). "Alpha cell insulin resistance may underlie the abnormal up-regulation of glucagon secretion Type 2 diabetes." (PMID 34659118, 2021). "Reflecting the HCD-induced increased IR, analysis of pancreatic β-cell function revealed that it was accompanied by a compensatory hyper-production of insulin and glucagon, followed by islet death typical of the pancreatic failure associated with established Type-2 diabetes in humans." (PMID 32163524, 2020). "However, there has been recent interest in using glucagon to treat obesity, and subsequently treat type 2 diabetes through weight loss." (PMID 29412829, 2018). "A recent study reported that genetic polymorphism in glucagon may be modified by smoking for the risk of type 2 diabetes." (PMID 29720110, 2018). "The miR-124-3p-iGluRs pathway was also implicated in enhanced glucagon secretion from islets treated long-term under high glucose, an effect referred to as glucotoxicity, which leads to the dysfunction of both α and β cells in type II diabetes." (PMID 27013590, 2016).
type 2 diabetes (continued). "Second, this phenomenon provides a mechanism accounting for the increase in plasma FGF21 concentration and hepatic FGF21 mRNA abundance observed in animals and patients with type 2 diabetes, a condition that is associated with an elevation in the plasma concentration of both glucagon and insulin." (PMID 24733293, 2014). "Loss of postprandial glucagon suppression is characteristic of type-2 diabetes." (PMID 21255422, 2011). "In contrast, the higher α-cell mass may reflect the resistance of α-cells to apoptosis in patients with type 2 diabetes and is associated with higher circulating levels of glucagon." (PMID 22140505, 2011). "Indeed, supraphysiological concentrations of GLP-1 have been found to correct both the deficient release of insulin and the excessive release of glucagon in type 2 diabetes." (PMID 19961265, 2009). "Because NO not only inhibits insulin release but also stimulates glucagon release this observation thus underlined a possible pathogenic role of the islet NO system in the development of type 2 diabetes." (PMID 18478125, 2008). "A post hoc analysis of data from two dietary studies in patients with type 2 diabetes reported that although isocaloric and hypocaloric diets both led to a similar improvement in hepatic steatosis, only the latter was associated with improvement in glucagon–alanine index." (PMID 38579751, 2024). "Type 2 diabetes mellitus (T2DM) is characterized by hyperglycemia and is caused by a combination of deficient insulin secretion, inadequate insulin resistance, and misleading glucagon secretion." (PMID 37998038, 2023). "Based on modeling of pooled glucose-clamp data, insulin resistance was associated with generally elevated glucagon and a potentiated cortisol-axis response to hypoglycemia, and over time both hormonal pathways may therefore contribute to dysglycemia and possibly type 2 diabetes." (PMID 36752854, 2023). "Type 2 diabetes mellitus (T2DM) is a category of complex metabolic disorders caused by an elevated level of glucagon secretion in the presence of insulin resistance (IR)." (PMID 34574525, 2021). "Administration of a somatostatin receptor antagonist (SSTR2a) increases glucagon counterregulation during hypoglycemia in rodent models of type 1 diabetes (T1D) but less is known about its effect on glucagon in type 2 diabetes (T2D)." (PMID 41502124, 2026). "Studies have reported expression of GCG in single-cell sequencing from SC-beta cells and human beta cells and co-expression of insulin and glucagon has been reported in type 2 diabetes." (PMID 41291239, 2026). "Interventions that suppress prandial glucagon secretion can reduce hyperglycaemia in type 2 diabetes, but timed targeting specifically to pancreatic alpha cells in vivo has proved difficult." (PMID 41174263, 2026). "In contrast, in the HHS group with all type 2 diabetes patients, the plasma glucagon level was positively correlated with serum CPR and serum CPR/plasma glucose ratio." (PMID 41292690, 2026). "Similar alterations in the islet cell phenotype occur in type 2 diabetes, in which an increase in the proportion of islet cells co-expressing insulin, glucagon and Nkx6.1, and glucagon with Nkx6.1, was found." (PMID 39860066, 2025). "In a phase 2b randomized trial involving adults with type 2 diabetes, cotadutide—another glucagon/GLP-1 receptor agonist—demonstrated significant improvements in glycemic control and body weight, compared to placebo (p < 0.001 for all measures)." (PMID 41153573, 2025). "The perturbation flows particularly affect β- and α-cells, which are specialized cells that secrete insulin and glucagon, respectively; their dysfunction is central to type 2 diabetes." (PMID 41465115, 2025). "Individuals with type 2 diabetes (T2D), characterized by impaired insulin action and enhanced glucagon secretion (hyperglucagonemia), resulting in hyperglycemia, have a higher risk of cognitive decline." (PMID 40271226, 2025).
type 2 diabetes (continued). "The pancreas regulates glucose homeostasis through the rhythmic secretion of insulin and glucagon into the portal circulation-an essential process that is disrupted early in the pathogenesis of type 2 diabetes." (PMID 42281561, 2025). "In mammals, glucagon and insulin are released in a pulsatile manner, which is disrupted in patients with type-2 diabetes, contributing to hyperglucagonemia." (PMID 39747032, 2025). "It stimulates glucose-dependent insulin secretion, suppresses glucagon release, and delays gastric emptying, making it a cornerstone in managing type 2 diabetes and obesity." (PMID 40806100, 2025). "This research clearly indicates that the interaction between neuronal glucose-sensing cells and islet α and β cells is essential for maintaining proper insulin and glucagon levels in the blood, a process that is impaired in type 2 diabetes." (PMID 40940782, 2025). "Positive co-staining with glucagon and vimentin has been reported in isolated case reports in biopsies from patients with chronic pancreatitis and type 2 diabetes." (PMID 39836539, 2025). "A similar level of insulin-immunoreactive cells, also containing either glucagon or somatostatin, has been reported within human islets and was increased in donors with type 2 diabetes." (PMID 39791735, 2025). "In this regard, novel dual and triple agonists that combine glucagon with incretin hormones have emerged as promising therapeutic options for both type 2 diabetes and obesity." (PMID 41149695, 2025). "The glucagon response was lower in people with type 1 diabetes (9.4 ± 0.8 pmol/L, 8.0 [7.0–10.0]) compared to type 2 diabetes (23.7 ± 3.7 pmol/L, 18.0 [12.0–28.0], p < 0.001) and controls (30.6 ± 4.7, 25.5 [17.8–35.8] pmol/L, p < 0.001)." (PMID 38376580, 2024). "In response to the glucagon infusion, the control group exhibited a larger increment in insulin levels compared to the type 2 diabetes group." (PMID 38276866, 2024). "Matching our results, a recently published study in individuals with type 2 diabetes found higher fasting and postprandial glucagon levels in men compared to women." (PMID 39599691, 2024). "Many biology and health textbooks use the actions of insulin and glucagon to illustrate homeostasis and feedback mechanisms but stop short of examining important environmental and social factors that contribute to type 2 diabetes diagnoses." (PMID 38549950, 2024). "The ingestion of fat alone has previously been shown to modestly increase prandial glucagon release in healthy subjects and subjects with type 2 diabetes." (PMID 39599691, 2024). "Mean steady-state plasma glucagon concentrations were slightly higher in the control group compared to the type 2 diabetes group, primarily due to the control subgroup with obesity having higher steady-state concentrations than the other three subgroups." (PMID 38276866, 2024). "After the meal, glucagon increased in the type 2 diabetes group (t=15 min to t=45 min; all p<0.001), whereas there was no change from fasting values in the NGT groups." (PMID 39138690, 2024). "The plasma levels of glucagon achieved with the analog in this study are higher compared with the levels seen in patients with both type 1 and type 2 diabetes." (PMID 39265079, 2024). "Compared with Lean-NGT, glucagon AUC240 was elevated in type 2 diabetes (p<0.001) and appeared greater in Obese-NGT (~55%; p=0.053)." (PMID 39138690, 2024). "We found that circulating amino acid levels were higher in type 2 diabetes and obesity, and that glucagon infusion decreased amino acid levels in both individuals with and without type 2 diabetes and obesity." (PMID 38276866, 2024). "This is consistent with previous studies, showing preserved glucagon responses to hypoglycaemia in people in earlier stages of type 2 diabetes." (PMID 38376580, 2024). "It is intriguing how from these data collectively an interplay emerges between insulin and glucagon pathways both involved in diabetes type 2, in which PON2 is involved." (PMID 38893310, 2024).
type 2 diabetes (continued). "Hyperglucagonemia is a hallmark of type 2 diabetes (T2DM), yet the role of elevated plasma glucagon (P-GCG) to promote excessive postabsorptive glucose production and contribute to hyperglycemia in patients with this disease remains debatable." (PMID 38265288, 2024). "It promotes insulin secretion and inhibits glucagon release in a glucose-dependent manner, making it known as a treatment for type 2 diabetes." (PMID 39596109, 2024). "These analogues enhance insulin secretion and inhibit glucagon release, thereby improving glycemic control, beneficial for individuals with type 2 diabetes." (PMID 39417406, 2024). "Elevated levels of glucagon, hyperglucagonaemia, are observed in several obesity-related diseases including type 2 diabetes and non-alcoholic fatty liver disease where it contributes to an increased risk of hyperglycaemia." (PMID 38276866, 2024). "These drugs enhance insulin secretion, suppress glucagon release, slow gastric emptying, and promote satiety, making them effective for managing type 2 diabetes and obesity." (PMID 39006724, 2024). "In type 2 diabetes (T2D), plasma glucagon levels are inappropriately high, thus contributing to the hyperglycemia phenotype that is the major hallmark of T2D6–8." (PMID 38879678, 2024). "Dysregulation of glucagon secretion, in the postprandial state, has been demonstrated in type 2 diabetes and pre-diabetic states." (PMID 36752854, 2023). "The insulin-antagonistic hormone glucagon has been suggested as a key player in the development of type 2 diabetes, along with other hormonal and neural systems." (PMID 36752854, 2023). "GIP stimulates glucagon secretion in healthy individuals and those with type 2 diabetes, especially at lower plasma glucose concentrations, whereas the insulinotropic actions are more prominent during hyperglycaemia." (PMID 37430117, 2023). "Tirzepatide is given to patients with type 2 diabetes after meals to stimulate insulin during both phases of its secretion and concurrently suppresses glucagon release, decreasing blood glucose levels." (PMID 37510690, 2023). "Reductions in the number of insulin-secreting β-cells in pancreatic islets with the simultaneous expansion of glucagon-secreting α-cells as well as insulin hypersecretion in the absence of insulin resistance often precede the onset of type 2 diabetes." (PMID 37274331, 2023). "In contrast, in people with type 2 diabetes, it raised fasting glucagon concentrations (7.9 ± 0.3 nmol/L versus 10.2 ± 0.3 nmol/L, P < 0.01) as well as nadir concentrations (6.8 ± 0.6 nmol/L versus 4.1 ± 0.4 nmol/L, P < 0.01) during the hyperglycemic clamp." (PMID 37751301, 2023). "GLP-1 suppresses glucagon secretion in healthy individuals and those with type 2 diabetes, especially at higher plasma glucose concentrations (while the counter-regulatory glucagon response in the case of hypoglycaemia remains unaffected)." (PMID 37430117, 2023). "The glucoregulatory actions of GLP-1RAs are well known and include glucose-dependent stimulation of insulin secretion and inhibition of glucagon release, resulting in a marked reduction in HbA1c in people with type 2 diabetes." (PMID 37542009, 2023). "In people with type 2 diabetes, fasting glucagon concentrations were markedly elevated and persisted despite hyperglycemia." (PMID 37751301, 2023). "Recent developments suggest that increased glucagon and decreased somatostatin secretion from the pancreas contribute to hyperglycaemia in type-2 diabetes (T2D) patients." (PMID 36834860, 2023). "In contrast, in people with type 2 diabetes, abnormalities in insulin and glucagon secretion rates persisted during hyperglycemia — in the latter case, to the point that hyperglycemia and hyperinsulinemia are insufficient to suppress EGP." (PMID 37751301, 2023).
type 2 diabetes (continued). "On the other hand, in people with type 2 diabetes, exendin 9-39 increased fasting (12 ± 2 pmol/min versus 17 ± 2 pmol/min, P = 0.01) and nadir (6 ± 1 pmol/min versus 9 ± 2 pmol/min, P = 0.02) glucagon secretion." (PMID 37751301, 2023). "Previously, it has been suggested that in people with type 2 diabetes, or perhaps in people with prediabetes more likely to progress to type 2 diabetes, increased glucagon secretion occurs to stimulate function in failing β cells." (PMID 37751301, 2023). "In patients with type 2 diabetes, the incretin effect is greatly impaired, which induces insufficient insulin secretion and insufficient suppression of glucagon secretion, resulting in postprandial hyperglycemia." (PMID 37762244, 2023). "Recently, the contribution of increased levels of circulating glucagon and decreased levels of somatostatin in type 1 and type 2 diabetes has been recognized as a contributor to hyperglycemia." (PMID 36834860, 2023). "Glucagon levels fall after carbohydrate ingestion, and insufficient post-prandial glucagon suppression can contribute to the development of type 2 diabetes." (PMID 36834794, 2023). "Although the islet pathology in type 2 diabetes is typically focused on insulin and beta cells, increased glucagon secretion and alpha cell function can also contribute to hyperglycemia in type 2 diabetes." (PMID 36144204, 2022). "The present study suggests that the glucagon test is more useful than other tests for assessing endogenous insulin secretory capacity in type 2 diabetic patients requiring hospitalization." (PMID 35574023, 2022). "KEGG analysis demonstrated that downregulated genes were related to maturity onset diabetes of the young, type II diabetes mellitus, calcium signaling pathway, and glucagon signaling pathway." (PMID 35851388, 2022). "Collectively, such findings are understandable if defective intra-islet glucagon action contributes to the characteristic loss of first-phase GSIS in an intravenous glucose tolerance test, that is, diagnostic of type 2 diabetes in the clinical setting." (PMID 34896391, 2022). "Type 2 diabetes is characterised by hyperglucagonaemia and perturbed function of pancreatic glucagon-secreting alpha cells but the molecular mechanisms contributing to these phenotypes are poorly understood." (PMID 35652923, 2022). "Obese, insulin-resistant humans and mice hypersecrete glucagon in the fed state, exacerbating hyperglycemia and encouraging the development of type 2 diabetes (T2DM)." (PMID 36002172, 2022). "Several works have demonstrated that in people with type 2 diabetes (T2D), the mechanisms that control the incretin effect are defective, leading to impaired regulation of insulin and glucagon secretion and exaggerated plasma glucose excursions after meals." (PMID 36230573, 2022). "The levels of d-Asp, which was detected in glucagon-secreting rodent alpha cells, were consistently lower in type 2 diabetes-affected islets in contrast to healthy islets." (PMID 36144204, 2022). "Abnormal postprandial suppression of glucagon in Type 2 diabetes (T2DM) has been attributed to impaired insulin secretion." (PMID 35822422, 2022). "The diabetogenic role of glucagon is widely accepted and confirmed in patients with type 2 diabetes." (PMID 36686477, 2022). "Downregulation of the mTOR/4E-BP1 signaling pathway in type 1 diabetes.Inhibition of glucagon signaling in type 2 diabetes." (PMID 36555754, 2022). "Insulin resistance, excessive or improper glucagon secretion, and insufficient insulin secretion are symptoms of type 2 diabetes mellitus (T2DM), a chronic endocrine metabolic disorder." (PMID 36419826, 2022). "The onset and progression of type 2 diabetes mellitus (T2DM) is due to relative insulin deficiency, but the contribution of impaired glucagon to T2DM is unclear." (PMID 35409362, 2022).